DCUN1D5 (defective in cullin neddylation 1 domain containing 5)
Description:
Contributes to the neddylation of all cullins by transferring NEDD8 from N-terminally acetylated NEDD8-conjugating E2s enzyme to different cullin C-terminal domain-RBX complexes which is necessary for the activation of cullin-RING E3 ubiquitin ligases (CRLs). May play a role in DNA damage response and may participate in cell proliferation and anchorage-independent cell growth.
Synonyms: DCNL5; SCCRO5; MGC2714; FLJ32431
Tractability: PROTAC: ubiquitination databases record sites on it; a small molecule that binds it is known.
Gene: Protein-coding gene on chromosome 11 (103,050,686 to 103,092,194, reverse strand). Ensembl gene ENSG00000137692.
Subcellular location: Nucleus; Cytoplasm, cytoskeleton, spindle
Subcellular location (Human Protein Atlas): Nucleoli; Nucleoplasm
Pathways (Reactome):
Metabolism of proteins: Neddylation
Gene Ontology:
Molecular function: cullin family protein binding; protein binding; ubiquitin conjugating enzyme binding; ubiquitin-like protein binding
Biological process: DNA damage response; positive regulation of protein neddylation; regulation of cell growth; regulation of protein neddylation; protein neddylation
Cellular component: nucleus; spindle; ubiquitin ligase complex
Genetic constraint (gnomAD): Loss-of-function variants: 3 observed, 17.52 expected, observed/expected ratio (o/e) 0.17, 90% interval 0.077 to 0.44. The upper end of that interval is the gene's LOEUF score, 0.44, which puts it in group 1 of 6, group 1 being the genes least tolerant of losing a copy. Missense variants: 81 observed, 155.79 expected, observed/expected ratio (o/e) 0.52, 90% interval 0.43 to 0.62. Synonymous variants: 58 observed, 53.3 expected, observed/expected ratio (o/e) 1.09, 90% interval 0.88 to 1.35.
Homologues: Orthologues: chimpanzee DCUN1D5 (100% identical), macaque DCUN1D5 (100% identical), pig DCUN1D5 (99% identical), rabbit DCUN1D5 (99% identical), dog DCUN1D5 (97% identical), rat Dcun1d5 (97% identical), mouse Dcun1d5 (96% identical), tropical clawed frog dcun1d5 (86% identical), zebrafish dcun1d5 (77% identical), guinea pig DCUN1D5 (62% identical), Drosophila melanogaster SCCRO4 (56% identical), Drosophila melanogaster SCCRO (28% identical), and 1 more. Paralogues in human: DCUN1D4 (69% identical), DCUN1D1 (30% identical), DCUN1D2 (30% identical), DCUN1D3 (27% identical).
Diseases named in the same sentence as DCUN1D5 in open-access papers:
DCUN1D5 is named in the same sentence as 19 diseases in open-access papers, as found by Europe PMC text mining. Sharing a sentence is not in itself a finding about the gene and the disease. The quoted sentences say what the papers report.
breast carcinoma (3 papers, 2021 to 2024). "Overexpression of DCUN1D5 was associated with reduced disease-specific survival in oral and lung squamous cell carcinomas and breast cancer." (PMID 35884544, 2022). "Importantly, high expression levels of DCUN1D5 were associated with a poor 5-year overall survival rate and relapse-free survival in breast cancer patients." (PMID 33918758, 2021). "Due to the relevance of DCUN1D5 expression in metastatic breast cancer, a better characterization of DCUN1D5 activity and its association with neddylation post-translation modifications will provide novel insights into breast cancer biology." (PMID 33918758, 2021). "DCUN1D5 expression was also identified to be elevated in high-metastatic TNBC breast cancers compared to low-metastatic luminal tumors in the TCGA-BRCA and CPTAC (Clinical Proteomic Tumor Analysis Consortium) dataset." (PMID 38831379, 2024). "For breast cancer, it is demonstrated that DCUN1D5 was highly expressed in metastatic breast tumors compared with non-metastatic breast tumors." (PMID 38831379, 2024). "In breast cancer, DCUN1D5 was identified to be highly expressed in metastatic breast tumors, especially for TNBC subtype." (PMID 38831379, 2024). "We found that DCUN1D5 expression was significantly higher in primary tumor samples than in normal samples in Perou breast cancer datasets (GSE10893 and GSE3521)." (PMID 33918758, 2021). "Collectively, our results strongly support a relevant role of high DCUN1D5 expression levels and reduced exon 4 skipping during metastatic progression of breast cancer." (PMID 33918758, 2021). "Here, we focused on DCUN1D5 splicing, however, future studies should understand how other identified AS events impact breast cancer progression and metastasis formation." (PMID 33918758, 2021). "To further investigate DCUN1D5 expression in breast cancer, we used The Cancer Genome Atlas (TCGA-BRCA) to compare non-pathological samples with primary breast tumors." (PMID 33918758, 2021). "Accordingly, we found high DCUN1D5 expression in breast cancer tissues with metastasis at distant sites compared to breast tumor without metastasis [Perou breast cancer dataset (GSE3521)]." (PMID 33918758, 2021). "Importantly, we also found a reduction of exon 4 skipping and high DCUN1D5 expression in breast cancer specimens (vs. normal tissues) and in high-metastatic subtypes (vs. low-metastatic breast tumors)." (PMID 33918758, 2021). "Finally, we compared 5-year overall survival rate of breast cancer patients with high and low DCUN1D5 expression levels." (PMID 33918758, 2021). "Based on these results, we next wondered whether the AS-NMD might be involved in regulating DCUN1D5 expression in metastatic breast cancer cells." (PMID 33918758, 2021). "Notably, we also found a significant negative correlation (r = −0.35; p-value = 0.016) between the percentage of NMD+ transcripts and total DCUN1D5 expression in breast cancer cell lines of the CCLE database." (PMID 33918758, 2021). "In addition, we also found that DCUN1D5 splicing profiles parallel DCUN1D5 expression levels in a wide panel of breast cancer cell lines present in the Cancer Cell Line Encyclopedia (CCLE) database." (PMID 33918758, 2021). "Nevertheless, even if we could not rule out the existence of additional mechanisms regulating total DCUN1D5 expression levels, our data suggest that an AS-NMD program activated by DCUN1D5 exon 4 skipping could contribute, at least in part, to control DCUN1D5 expression in breast cancer cells." (PMID 33918758, 2021). "Moreover, they support the conclusion that SRSF1 activation could contribute to the malignant progression of breast cancers by stabilizing DCUN1D5 expression through the involvement of the AS-NMD pathway." (PMID 33918758, 2021). "To support the involvement of DCUN1D5 in breast cancer cell biology, we overexpressed GFP-tagged DCUN1D5 in low-metastatic MCF7 cells." (PMID 33918758, 2021).
breast carcinoma (continued). "In particular, breast cancer cell lines with high metastatic potential (TNBC subtype) showed high levels of DCUN1D5 exon 4 inclusion and high DCUN1D5 expression levels compared to breast cancer cell lines with low metastatic potential (luminal subtype)." (PMID 33918758, 2021). "To demonstrate the involvement of the NMD pathway in regulating DCUN1D5 expression, we treated MCF7 breast cancer cells with cycloheximide (CHX), a well-known NMD inhibitor." (PMID 33918758, 2021). "Notably, overexpression of different SR proteins, such as SRSF3, was not able to alter the DCUN1D5 exon 4 splicing profile in breast cancer cells." (PMID 33918758, 2021).
breast tumor (2 papers, 2021 to 2024). "Patients who expressed high DCUN1D5 levels in breast tumors from the TCGA-BRCA dataset exhibited a significantly lower survival rate than patients with lower DCUN1D5 expression." (PMID 33918758, 2021). "To determine the DCUN1D5 expression levels in breast tumors, we interrogated various cancer databases." (PMID 33918758, 2021). "Notably, protein expression of DCUN1D5 was also up-regulated in both TNBC and HER2 positive breast tumors compared to luminal ones as determined using data from the Clinical Proteomic Tumor Consortium (CPTAC) Confirmatory/Discovery dataset retrieved by UALCAN web-tool." (PMID 33918758, 2021). "We next wondered whether DCUN1D5 was expressed differently in metastatic breast tumors compared to non-metastatic tumors." (PMID 33918758, 2021).
cervical cancer (1 paper, 2021). A primary or metastatic malignant neoplasm involving the cervix. "Interestingly, a homologous to DCUN1D1 gene, DCUN1D5 is located at 11q22 and is amplified in 8.1% of samples in cervical cancer TCGA cohort." (PMID 34436017, 2021).
lung carcinoma (1 paper, 2024). "Recent study has indicated that DCUN1D5 was linked with multiple cancers, including oral and lung cancer." (PMID 38831379, 2024).
lymph node metastasis (1 paper, 2024). "Clinicopathological analysis revealed that high DCUN1D5 expression was positively correlated with lymph node metastasis (p = 0.014) and lymphovascular invasion (p = 0.020)." (PMID 38831379, 2024).
prostate tumor (1 paper, 2026). "SETD6 KO GO Group 2 contains genes promoting prostate tumor growth and migration via regulation of ubiquitin transferases, including DCUN1D5, UBE2S, and CDC20." (PMID 41540805, 2026).
triple-negative breast carcinoma (1 paper, 2024). An invasive breast carcinoma which is negative for expression of estrogen receptor (ER), progesterone receptor (PR), and human epidermal growth factor receptor 2 (HER2). "In the present study, we explored the role of DCUN1D5 in the development of triple-negative breast cancer and evaluated its prognostic value for patients with TNBC." (PMID 38831379, 2024). "By using the RNA-Seq analyses, we revealed that PI3K/AKT signaling pathway was a dominant component in the enriched pathways regulated by DCUN1D5 in triple-negative breast cancer." (PMID 38831379, 2024). "To identify the upstream transcriptional regulation for DCUN1D5 in triple-negative breast cancer, we used JASPAR database and PROMO software to screen for the potential transcriptional factors." (PMID 38831379, 2024). "The findings of this study provide novel insights of DCUN1D5 in the progression of TNBC and suggest a new theoretical basis for the prevention and treatment of patients with triple-negative breast cancer." (PMID 38831379, 2024). "Taken together, these findings provide novel insights of DCUN1D5 in the progression of TNBC and suggest a new theoretical basis for the treatment of triple-negative breast cancer." (PMID 38831379, 2024).
cancer (6 papers, 2015 to 2025). A tumor composed of atypical neoplastic, often pleomorphic cells that invade other tissues. "Our study reported for the first time that DCUN1D5 could affect the PI3K/AKT signaling pathway in TNBC, which further supplemented the mechanistic investigation of DCUN1D5 in cancer." (PMID 38831379, 2024). "Finally, supported by the relevance of DCUN1D5 in different cancer types, we focused our attention on DCUN1D5 exon 4, an AS change identified by our RASL-seq analysis." (PMID 33918758, 2021). "DCUN1D5 was found to be up-regulated in different cancer types, whereas its elevated expression levels were reported to increase cell proliferation, migration, and invasion, thus suggesting the involvement of DCUN1D5 in cancer progression." (PMID 33918758, 2021). "Another publication demonstrated that YY1 activates DCUN1D5 acting on the PI3K/AKT pathway, which stimulates cancer progression in TNBC patients." (PMID 41009346, 2025).
tumor (4 papers, 2016 to 2024). "By TCGA dataset and surgical specimens with immunohistochemical (IHC) staining method, DCUN1D5 was identified to be significantly upregulated in TNBC tumor tissues and negatively associated with prognosis." (PMID 38831379, 2024). "It was indicted that DCUN1D5 protein level was also significantly elevated in the TNBC tumor tissues than in the corresponding adjacent normal tissues." (PMID 38831379, 2024). "The genomic instability of the miR-34a-high tumor cell line was reflected in high-copy amplicons coding for the oncogenes Yap1, Birc2, Birc3, Dcun1d5 (all on 9A1) or the leptin receptor (4C6)." (PMID 26871287, 2016). "In summary, these findings indicate that DCUN1D5 could promote tumor growth and metastasis of TNBC in vivo." (PMID 38831379, 2024). "To elucidate the expression pattern of DCUN1D5 in TNBC, we firstly explored DCUN1D5 mRNA level based on TCGA dataset and identified that DCUN1D5 was highly expressed in TNBC tumor tissues than in normal breast tissues (p < 0.001)." (PMID 38831379, 2024). "ANKRD13B, ISG15, KBTBD12, KLHL35, and UHRF1 were upregulated in tumor samples; DCUN1D5, HCK, and SOCS3 were downregulated in tumor than in normal samples." (PMID 35884544, 2022). "Accordingly, DCUN1D5 expression was increased in high-metastatic compared to non-metastatic tumor tissues." (PMID 33918758, 2021).
DCUN1D5 also shares sentences with these, for which no sentence is quoted: lung squamous cell carcinomas (3 papers); ductal carcinoma in situ (1); infection (1); invasive carcinoma (1); invasive ductal carcinoma (1); medullary carcinoma (1); metastatic tumors (1); phyllodes tumor (1); rhabdoid tumor (1); tubular carcinoma (1).